PIK3CA (phosphatidylinositol-4,5-bisphosphate 3-kinase catalytic subunit alpha)
Diseases named in the same sentence as PIK3CA in open-access papers (continued):
Sharing a sentence is not in itself a finding about the gene and the disease.
tumor (continued). "Factors that were associated with statistically significantly worse OS in this analysis included an age of <50 years (p=0.016), right-sided tumor origin (p<0.001), poor differentiation (p<0.001), KRAS mutations (p<0.001), BRAF mutations (p=0.004), and PIK3CA mutations (p=0.007)." (PMID 28424412, 2017). "Although this study used biomarker-driven patient selection, PTEN loss and PIK3CA amplification/mutation alone were not sufficient for predicting the anti-tumor activity of everolimus." (PMID 28330462, 2017). "However, although long-term stabilization and partial tumor responses have been observed in PIK3CA-mutant cancers treated with PI3K inhibitors, the majority of PIK3CA- mutant cancers do not show substantial regression in clinical trials." (PMID 28036259, 2017). "The presence of PIK3CA mutation in the primary tumor alone is not a sufficient predictive marker of efficiency." (PMID 29404273, 2017). "Because autophagy is one of the adaptive mechanisms of resistance to inhibition of the PI3K–AKT pathway, we studied whether autophagy inhibition could augment the anti-tumor efficacy of PI3K inhibitor in PIK3CA-mutant or wild-type cancer cell lines." (PMID 28036259, 2017). "The study did not meet its primary objective of demonstrating the anti-tumor activity of everolimus in PIK3CA amplification/mutation and/or PTEN loss patients with advanced solid tumors refractory to standard therapy." (PMID 28330462, 2017). "On contrary, the levels of cfDNA mutations in patients without a prior KRAS/NRAS/BRAF/PIK3CA tumor mutation were 10-fold lower than the mutation cutoff (p = 0.002)." (PMID 27852040, 2017). "In contrast, this specific FFL was not significantly enriched in any of the non PIK3CA-mutated luminal A tumor samples." (PMID 28392480, 2017). "For patient 2, mutations in PIK3CA and CHEK2 were identified in all tumour regions and may be potential therapeutic targets (drugs are still being tested in clinical trials)." (PMID 28916750, 2017). "These tumor-based markers should be expanded so that not only genomic aberrations in PIK3CA, PTEN, ATKT1/2, etc. could be targeted, but also a ‘PI3Kness’ status is included that can serve as indicator for all activating alterations." (PMID 29113422, 2017). "LB-Seq detected one mutation not evident in BM-derived tumour DNA, PIK3CA p.Y207* at 0.28% cfDNA AF in MYL-001." (PMID 28492226, 2017). "We observed a perfect match (100% specificity and sensitivity of the BEAMing technique compared to Ion Torrent and Cobas FDA-approved tumor mutation assessment kits) in the results of our analysis of KRAS, NRAS, PIK3CA and BRAF mutations in tumor and prior treatment plasma samples." (PMID 27852040, 2017). "Because mutations in the PI3K/Akt pathway located in AKT1, AKT2, AKT3, PTEN, and PIK3CA were analyzed altogether, their results did not provide any direct insights on the association between PIK3CA mutation status and primary tumor location." (PMID 29207615, 2017). "However, GLUT1 levels in PIK3CA-amplified ADC tumours were significantly lower (3.3-fold) than SqCC tumours, suggesting additional histology-specific regulation of GLUT1 expression in SqCC." (PMID 28548087, 2017). "Moreover, significant tumor regression was observed in animals bearing HER2-amplified and PIK3CA-mutated breast, colon or NSCLC tumors treated with BAY 80–6946." (PMID 28592260, 2017).
tumor (continued). "In the present study, somatic PIK3CA mutations were found in 24.3% of tumours, and ERBB family mutations were found in 10.8% of tumours, with a similar distribution in ER-positive or ER-negative tumours, which confirms results of previous studies." (PMID 28750640, 2017). "Furthermore, we demonstrate that although everolimus and palbociclib are efficacious in the CTC-174 model (D538G ER, N345K PIK3CA), more potent tumor regressions were observed when these agents were combined with fulvestrant." (PMID 27472462, 2016). "PIK3CA mutations and subsequent activation of the PI3K/AKT pathway play an essential role in cancer cell signaling pathways, involving growth factors, cytokines, and other cellular stimuli associated with human neoplasms." (PMID 27388016, 2016). "Of the 125 cases, 101 tumor samples were evaluable for PIK3CA FISH analysis." (PMID 27016421, 2016). "All of these genes have been associated with tumor growth and progression, and recent studies suggest that additional mutations in KRAS and NRAS, as well as downstream mutations in BRAF or PIK3CA, may cause resistance to anti-EGFR treatment." (PMID 26989027, 2016). "Among the tumor samples tested, 52% of samples had at least one alteration in PIK3CA, PTEN, or AKT." (PMID 27826244, 2016). "An additional PIK3CA mutation located in exon 20, the c.3140A>G (p.H1047R), was detected in the metastatic lymph node sample examined from a MBC case whose primary tumor was PIK3CA mutation negative." (PMID 27765917, 2016). "In pre-clinical studies, WX-037 demonstrated strong inhibition of AKT phosphorylation, and promising growth inhibition in a range of cell lines in vitro, and tumour growth delay or stasis in vivo, with greater sensitivity observed in PIK3CA mutant or PTEN null cells and tumours." (PMID 27837257, 2016). "To assess the sensitivity of the method, we constructed the plasmids carrying the 126-bp fragment of wild-type and homozygous mutant-type PIK3CA and diluted the homozygous mutant plasmid in increasing concentrations of the wild-type plasmid to mimic tumor heterogeneity." (PMID 27405731, 2016). "No obvious clinical characteristics correlated with PIK3CA mutations except tumor staging at initial diagnosis." (PMID 27734950, 2016). "The association between BM and mutation in PIK3CA and BRAF, expression of NCAM, EGFR, and CXCR4, MGMT methylation and increase in the tumor marker CA19.9 have also been investigated, but only in one or two studies each and on small samples, so the possible predictive potential is hard to determine." (PMID 27037031, 2016). "Only in a single case was a mutation detected in blood but not in tumor; in another case, a different PIK3CA mutation was detected in tumor compared with blood." (PMID 27515171, 2016). "Nonetheless, tumor response to PIK3R2 depletion did not require PIK3CA, PTEN or KRAS mutation, and caused shrinkage of all tumors examined with enhanced p85β expression." (PMID 27835880, 2016). "Interestingly, cleaved caspase-3 was potently induced by the combination therapy in PIK3CA+ cells in vitro and tumor xenografts." (PMID 26882569, 2016). "Although AOA is a pan-aminotransferase inhibitor, our data clearly demonstrate that the tumour inhibitory effect of AOA on PIK3CA mutant xenografts is indeed on-target to GPT2, because GPT2 knockdown cells grow much slower in nude nice and these tumours are insensitive to AOA treatment." (PMID 27321283, 2016).
tumor (continued). "Twenty percent of ccRCC have mutations in MTOR, TSC1, PIK3CA, and PTEN and indicates that deregulated mTOR pathways may also be critical in this tumor subtype." (PMID 27530247, 2016). "Likewise, we screened the prime targets of these miRNAs (EGFR and PIK3CA) and discovered that they were both significantly upregulated in the tumor tissues." (PMID 27095166, 2016). "Both pmTOR and pS6RP were found to be significantly more highly expressed in tumour than normal tissue, and phosphoprotein expression did not correlate with PIK3CA mutation status here." (PMID 27765909, 2016). "We confirmed that PIK3CA mutations have no prognostic role in this type of cancer, whereas tumor grade and size, lymph node involvement and stage are significantly associated with PFS and OS." (PMID 27886225, 2016). "As EGFR acts through the PIK3CA/AKT pathway, mutations in that pathway might be anticipated to provide a resistance mechanism for the tumor cells." (PMID 27304188, 2016). "Conversely, mutations in PIK3CA were prognostic in patients with ER− tumours (HR=1.4, CI=1.1–1.9), but not in those with ER+ tumours (HR=1.1, CI=0.9–1.3)." (PMID 27161491, 2016). "Analysis of DNA extracted from 2008 (pre-trial) tissue showed that the tumor harbored wild-type EGFR, and a PIK3CA mutation was detected in plasma, but not tumor DNA." (PMID 27200287, 2016). "Analysis of archival primary tumor samples from the 37 patients in the responder analysis set showed that, of the non-responders, two additional patients were identified as PIK3CA mutation positive." (PMID 26931343, 2016). "Of the three tumours with PIK3CA mutations detected at surgery, but not at baseline, two were collision tumours, where the second tumour containing mutant PIK3CA was missed by the initial biopsies." (PMID 27502118, 2016). "However, anecdotal reports have described remarkable responses in salivary tumors when genetic aberrations and therapies were matched: trastuzumab and lapatinib for Her2-aberrant salivary tumors or mTOR inhibitors for PIK3CA-aberrant neoplasms." (PMID 26247885, 2015). "This is best illustrated by an activating PIK3CA mutation (H1047R) which was clonal in the primary tumor, but completely absent from either the metastasis or cfDNA." (PMID 26317216, 2015). "Importantly, the PIK3CA mutations and BRAF mutations, occurring in cases with wild-type KRAS, are known to be mechanistically activating and are enriched in other tumour types." (PMID 25855536, 2015). "At the histological level, ~80% of the liver parenchyma from PIK3CA/Yap mice was occupied by tumor lesions, with the remaining liver tissue consisting of lipid-rich hepatocytes (morphologically identical to those detected in PIK3CA mice) and normal liver tissue." (PMID 25826091, 2015). "In agreement with previous findings, with the exception of two cases, PTEN loss and PIK3CA mutation status were not present within the same tumor samples in the present study." (PMID 25621052, 2015). "Very similar figures have been reported for PIK3CA mutant tumours." (PMID 25943333, 2015).
tumor (continued). "Furthermore, the expression and location of c-MET and PIK3CA proteins were also studied by IHC in resected tumor tissues." (PMID 26334097, 2015). "A more recent type of population enriched design ignores traditional tumor histologic origin and classification (eg, gastric, lung etc.)by enriching for a certain biomarker, such as PIK3CA mutation or MET amplification, irrespective of tumor histology." (PMID 25557400, 2015). "The present study revealed that PIK3CA mutations were more common in MSI and BRAF mutated tumours." (PMID 25884297, 2015). "Notably, the c-index significantly increased from 0.63 to 0.87 when PIK3CA amplification was added to a model including extracapsular spread and pathological tumor stage for predicting disease-specific survival (p = 0.00006)." (PMID 26087196, 2015). "We used in vivo electroporation in the mouse retina to ascertain if PIK3CA, AKT, and FOXO1 could substitute for PTEN loss in the control of RB/E2F-induced retinal apoptosis and tumor emergence." (PMID 25907958, 2015). "CDK 4/6-PI3K inhibition is very effective in several PIK3CA mutant xenograft tumor models." (PMID 25990212, 2015). "In patient #2 we observed an activating PIK3CA mutation in the primary tumor that was not seen in either the liver metastasis or cfDNA." (PMID 26317216, 2015). "This resistance was specifically linked to changes in the level of phosphorylation of 4E-BP1, and was not evident in either a tumor with wild type KRAS or a tumor with a PIK3CA mutation in addition to KRAS." (PMID 24393708, 2014). "Although the mutation status of EGFR or other key genes in these patient tumor-derived cells is unknown, the status of KRAS, PIK3CA, or PTEN was mostly wild type." (PMID 25466244, 2014). "The PIK3CA expression status was examined in 406 ESCC tumor tissues and 223 paired normal tissues." (PMID 25054828, 2014). "In a second case, a patient with a PIK3CA mutation in the metastatic sample showed PTEN loss in the primary tumor, though the metastatic sample was not evaluable for PTEN." (PMID 24520381, 2014). "Likewise either mutation of PIK3CA or silencing of PTEN and subsequent activation of AKT is a frequent form of oncogene addiction in many tumour types." (PMID 25361007, 2014). "In the present study, we examined PIK3CA gene mutation, PIK3CA amplification as well as the expression of PI3K p110α, p-Akt, mTOR and PTEN which lie in the PI3K pathway in a consecutive collection of NSCLC tumor samples." (PMID 24533074, 2014). "The median ages of patients whose tumor tissue contained mutations of KRAS, PIK3CA and NRAS (54.5, 58.0 and 56.0 years, respectively) were lower than that of patients containing all-wild types of KRAS, BRAF, PIK3CA and NRAS (median age, 64.0 years)." (PMID 24774510, 2014). "Finally, we showed that PKD1 expression does not correlate with classical clinical and pathological prognostic factors (SBR histological grade, macroscopic tumour size, PR and ERBB2 statuses and PIK3CA mutation status)." (PMID 25287328, 2014). "We examined KRAS mutations in codons 12, 13, 61 and 146 (assessed by pyrosequencing), in relation to clinicopathological features, and tumor molecular markers, including BRAF and PIK3CA mutations, CpG island methylator phenotype (CIMP), LINE-1 methylation, and microsatellite instability (MSI)." (PMID 24885062, 2014).
tumor (continued). "The PIK3CA status can be easily assessed on tumour biopsies or liquid biopsies, and this molecular alteration may be predictive of response to dual targeting against HER2 receptor." (PMID 25374620, 2014). "In our study sample, 29% of tumours presented with either a hotspot (HS, 71%) or a nonhotspot (non-HS, 29%) PIK3CA mutation." (PMID 24981670, 2014). "In the other studies, patients were younger, and the group of patients with nonlobular breast cancer included hormone receptor-negative patients, who are more often high tumor grade, and are less often PIK3CA-mutated." (PMID 24467828, 2014). "In addition, future studies should assess basal levels of TS expression in tumor tissue and stratify patients based on status of PIK3CA and PTEN to validate potential predictive markers." (PMID 24658085, 2014). "Comparison of the clinicopathological features of the mutated KRAS, PIK3CA, NRAS genes with an all-wild type of these genes showed that the frequency of the intestinal type was significantly higher in patients whose tumor tissue contained KRAS mutations (P = 0.014)." (PMID 24774510, 2014). "In this study, we show that the combination of a selective MEK inhibitor and a PI3K/mTOR inhibitor is effective against tumor cell lines refractory to gefitinib by three different mechanisms: an EGFR gatekeeper T790M mutation, MET amplification, and KRAS/PIK3CA mutation." (PMID 24939055, 2014). "Oncogenic RAS co-operates with other oncoproteins, as in the case of requirement for interaction of PI3-kinase p110α with RAS in lung tumour maintenance, or the study where single copies of mutant KRAS and mutant PIK3CA cooperate in immortalized human epithelial cells to induce tumour formation." (PMID 25361007, 2014). "One tumour arising in a BRCA1 carrier had an exon 20 PIK3CA mutation, five PIK3CA mutations occurred in BRCAX males whereas no PIK3CA mutation were identified in tumours from BRCA2 mutation carriers." (PMID 23971979, 2013). "The p.Thr58_Met72dup duplication occurred in one tumor carrying a PIK3CA p.His1047Tyr substitution." (PMID 23548132, 2013). "Patient 9's tumor had notable mutations in KRAS (G12R) and PIK3CA (R93W)." (PMID 24204627, 2013). "Subsequently, doses of 75-150 mg/kg have been shown to result in tumour growth inhibition in a range of human tumour xenograft models including tumours that are PIK3CA mutant, PTEN null, EGFR mutant or wild type, with an associated decrease in AKT and S6 phosphorylation." (PMID 24339963, 2013). "We combined tumour mutation data from the Cancer Genome Atlas with matched patient genetic data, and tested for germline variants that associate with somatic mutation of the EGFR pathway (including EGFR, KRAS, BRAF, PTEN and PIK3CA)." (PMID 24152305, 2013). "The PIK3CA sequence variation identified was not present in normal adjacent tissues, indicating that these variants are tumor specific and somatically acquired mutations." (PMID 23809582, 2013). "PIK3CA activating mutations, clustered in exons 9 (helical domain) and 20 (kinase domain) have been reported in 18–40% BC, occasionally associated with HER2 phenotype and tumour recurrence." (PMID 22454081, 2012). "KRAS mutations (G12V and G13D) (n = 3) and the PIK3CA H1047R mutation (n = 1) were detected in FFPE tumor samples, but no mutations were found in any cpDNA samples." (PMID 23144797, 2012). "Therefore, the occurrence of functional integrity of the RAS-driven pathways - BRAF-MEK-ERK and PIK3CA-AKT - is necessary in order to really interfere with tumour cell growth through inhibition of EGFR target." (PMID 22931052, 2012). "However, in cases where a limited amount of tumor tissue was available, the majority of time we examined the PIK3CA gene with the DsX kit or direct sequencing, due to concern regarding mRNA quality in archival samples." (PMID 23342270, 2012).